STMN2 (stathmin 2)
Diseases named in the same sentence as STMN2 in open-access papers (continued):
Sharing a sentence is not in itself a finding about the gene and the disease.
diabetes (2 papers, 2022 to 2026). "In NOD mice, although diabetes incidence was lower in males than in females, diabetic male mice displayed comparable loss of islet sympathetic innervation and reduced expression of Gap43, Tubb3, and Stmn2." (PMID 41243316, 2026). "In conclusion, our findings suggest a proof-of-concept model in which diabetes suppresses trafficking of glucagon and Stmn2 from the late endosome toward the Lamp2A+ lysosomes." (PMID 34923907, 2022). "In the present study, we show that in STZ-induced diabetes in male mice, the abnormally high secretion of glucagon is accompanied by a relative decrease in cellular Stmn2." (PMID 34923907, 2022). "However, following induction of diabetes, Rab7 maintained colocalization with glucagon, and did appear to colocalize with Stmn2." (PMID 34923907, 2022). "This apparent uncoupling of Stmn2 and glucagon suggests that Stmn2 is required for the trafficking of glucagon to Lamp2+ lysosomes in the normal regulation of glucagon secretion, and that, in diabetes, this step is impaired." (PMID 34923907, 2022). "We hypothesize that a disruption in the trafficking of glucagon and Stmn2 through the endolysosomal pathway might be a possible mechanism by which glucagon secretion becomes dysregulated in diabetes, resulting in glucagon hypersecretion and hyperglucagonemia." (PMID 34923907, 2022). "We hypothesized that disruption of Stmn2-mediated trafficking of glucagon to the endolysosomes in diabetes contributes to hyperglucagonemia." (PMID 34923907, 2022). "Therefore, glucagon hypersecretion in diabetes could be a result of enhanced retrograde trafficking of glucagon and Stmn2 from the late endosome toward the TGN, and then through the regulated secretory pathway." (PMID 34923907, 2022). "Thus, the enhanced secretion of Stmn2 in diabetes may reflect an elevation in exocytotic activity in hyperglucagonemia, and not increases in mRNA or protein synthesis." (PMID 34923907, 2022). "Importantly, cell Stmn2 content was reduced in islets of diabetic mice, and further reduced after Arg stimulation, thereby showing a different profile from that of glucagon in diabetes." (PMID 34923907, 2022). "Following induction of diabetes, colocalization of EEA1 with glucagon (PCC 0.03 ± 0.07) or Stmn2 (PCC 0.04 ± 0.07) still remained very weak." (PMID 34923907, 2022). "In contrast, STZ-induced diabetes significantly reduced levels of colocalization between glucagon and Lamp2A (PCC 0.14 ± 0.03; p < .001) and also between Stmn2 and Lamp2A (PCC 0.15 ± 0.03; p < .001)." (PMID 34923907, 2022).
liver fibrosis (2 papers, 2023 to 2025). "STMN2 has been profiled in early-stage liver fibrosis in patients with chronic hepatitis C virus infection, and its expression has been positively correlated with insulin resistance in NASH." (PMID 38224712, 2023).
ovarian carcinoma (2 papers, 2015 to 2020). A malignant neoplasm originating from the surface ovarian epithelium. "In conclusion, through an integrated bioinformatics analysis, STMN2 was screened as a hub gene, mostly associated with the metastasis of ovarian cancer, and its functions and pathways involved in the ovarian cancer were explored." (PMID 32510146, 2020). "The high expression of STMN2 in ovarian cancer tissue was verified in mRNA and protein level compared with normal ovarian tissue, which is consistent with the results of Oncomine database." (PMID 32510146, 2020). "STMN2 was highly expressed in ovarian cancer cell lines (SK-OV3, A2780, and HO-8910) compared with normal cell lines (IOSE-80)." (PMID 32510146, 2020). "Further studies to explore functions and mechanism of STMN2 in ovarian cancer metastatic process will be performed in our future work." (PMID 32510146, 2020). "The Cancer Genome Atlas (TCGA) suggested that the up-regulated expression of STMN2 was related to poor prognosis of ovarian cancer." (PMID 32510146, 2020). "ONCOMINE analysis showed that STMN2 transcripts were 1.116-fold higher in cancer compared with normal samples from Bonome Ovarian Statistics (P = 6.37E−5), indicating that the expression of STMN2 was up-regulated in ovarian cancer." (PMID 32510146, 2020). "The quantitative reverse transcription-polymerase chain reaction (qRT-PCR) and western blot showed that STMN2 was highly expressed in ovarian cancer tissue and ovarian cancer cell lines." (PMID 32510146, 2020). "STMN2 was highly expressed in ovarian cancer tissue and cell lines." (PMID 32510146, 2020). "STMN2 expression was further verified in ovarian cancer by using FireBrowse and ONCOMINE database." (PMID 32510146, 2020).
prostate carcinoma (2 papers, 2015 to 2024). A carcinoma that arises from epithelial cells of the prostate gland. "Module 2 includes COL3A1, COL5A2, and NOTCH3, which have been reported to be associated with metastasis in prostate cancer, as well as HEYL, STMN2, and ASPN, which have been implicated in prostate cancer progression." (PMID 39347576, 2024).
steatosis (2 papers, 2018 to 2020). Increased lipid within the cytoplasm of cells. "Six progress-related genes (AKR1B10/SPP1/CD24/UBD/FABP4/STMN2) were found remarkably correlated with steatosis, ballooning, inflammation, fibrosis, and NAS in the progress of Normal/NAFL/NASH." (PMID 33574818, 2020).
Type 2 diabetes (2 papers, 2020 to 2022). "In the human islet, Stmn2 expression may be unique to alpha cells, as shown by genome-wide RNA-Seq analysis and single cell transcriptomics, and alpha cell Stmn2 mRNA expression is differentially regulated in type 2 diabetes." (PMID 32117057, 2020).
embryonic carcinoma (1 paper, 2025). "In transcriptome-wide RNA-binding profiles of selected SRSF proteins conducted in a murine embryonic carcinoma cell line, we noticed that SRSF7 interacts with Stmn2 based on iCLIP (individual-nucleotide resolution UV crosslinking and immunoprecipitation) results." (PMID 40140908, 2025).
glaucoma (1 paper, 2022). Increased pressure in the eyeball due to obstruction of the outflow of aqueous humor. "A potential link may exist for glaucoma pathogenesis via axonal survival factors, such as nicotinamide mononucleotide adenylyltransferase 2 (NMNAT2) and stathmin 2 (STMN2)." (PMID 36012964, 2022).
medulloblastoma (1 paper, 2020). A malignant, invasive embryonal neoplasm arising from the cerebellum. "Unexpectedly, the expression of STMN2 and GRIA2 was comparable in the medulloblastoma subtypes compared to the normal cerebellum, apart from the GRIA2 expression (p < 0.001) in the WNT and Group 3 subtypes." (PMID 32720471, 2020).
osteoarthritis (1 paper, 2022). A noninflammatory degenerative joint disease occurring chiefly in older persons, characterized by degeneration of the articular cartilage, hypertrophy of bone at the margins and changes in the synovial membrane. "The classification model constructed by LASSO analysis showed that six genes including CDKN1A, FOSB, STMN2, SLC2A3, TAC, and SCRG1 can be used as biomarkers of osteoarthritis, and the SCRG1 gene shows importance in osteoarthritis." (PMID 35720295, 2022).
ovarian tumor (1 paper, 2020). "The association of STMN2 expression level with immune infiltration abundance in ovarian tumor was evaluated using TIMER database." (PMID 32510146, 2020).
Rett syndrome (1 paper, 2021). A severe neurodevelopmental disorder affecting the central nervous system.
Sensory neuropathy (1 paper, 2024). Peripheral neuropathy affecting the sensory nerves. "Constitutive Stmn2 knockout (Stmn2−/−) induces severe motor and sensory neuropathy, including decreased compound muscle action potentials, NMJ denervation, and reduced nerve fiber density." (PMID 38600555, 2024).
serous ovarian cancer (1 paper, 2023). "STMN2 has been indicated to be differentially expressed in metastatic and non-metastatic samples of serous ovarian cancer, and high level of STMN2 is associated with poor prognosis of patients." (PMID 36790659, 2023).
tumor (11 papers, 2020 to 2025). "Comprehensive scRNA-seq analysis, with in vitro experiments, investigated the mechanisms by which STMN2+ TAMs influence tumor progression and immune exhaustion." (PMID 41438751, 2025). "Intratumoral heterogeneity was also evident in this analysis as for example characteristic marker genes for aNSCs (Hes6), TACs (Ube2c) and NBs (Stmn2) are expressed to different extents in the different tumor cell populations." (PMID 37407554, 2023). "Among these, CCNA1 and STMN2, which we found to be upregulated in the non-tumor infected patient-derived organoids, were previously identified to be upregulated in HCC." (PMID 34328417, 2021). "In addition, we found the same lineage-defining genes of the murine trajectory (DBI, HMGN2, STMN2) selectively expressed among the human tumor cells." (PMID 40562749, 2025). "Subsequently, we examined the spatial k-distance between TAM subpopulations and T cell subtypes across each tumor section, showing that in responders, STMN2+ TAM were in closer proximity to Tem/Teffe cells, whereas in non-responders, STMN2+ TAM were closer to CD8+ Tex cells." (PMID 41438751, 2025). "However, functions and pathways of STMN2 in tumor-infiltrating lymphocytes need further study." (PMID 32510146, 2020). "The CellTrek mapping analyses effectively visualized the spatial distribution of SPP1+ TAM, STMN2+ TAM, APOE+ TAM, Tregs, CD8+ Tex cells, and Tem/Teffe cells within tumor sections, revealing their substantial infiltration in TIME." (PMID 41438751, 2025). "Tumor cells were characterized by high expression of NB tumor signature genes (PHOX2B, HAND2, STMN2, and KCNQ2), which were exclusively expressed in the BM of metastatic patients with NB." (PMID 38358826, 2024). "Overall, the spatially resolved stRNA-seq analysis revealed that the proximity between STMN2+ TAM and CD8+ Tex cells may significantly influence the response to immunotherapy in tumor patients." (PMID 41438751, 2025). "Furthermore, we performed Spatalk analysis to elucidate the spatial communication patterns between STMN2+ TAM, CD8+ Tex cells and Tem/Teffe cells in tumor sections, investigating the ligand-receptor interactions (LRIs) between LGALS1 and PTPRC." (PMID 41438751, 2025). "Subsequently, by integrating the cell-to-cell k-distance across all tumor sections, we assessed the spatial k-distance to STMN2+ TAM in both responders and non-responders." (PMID 41438751, 2025). "IL1RL1, PCDHGA3, STMN2, and UGT2B11 showed no expression with tumor microenvironment components." (PMID 37985782, 2023).
cancer (8 papers, 2020 to 2025). A tumor composed of atypical neoplastic, often pleomorphic cells that invade other tissues. "Pan-cancer STMN2.SIG performed well in predicting immunotherapy response in pan-cancer cohorts, potentially linked to intercellular interactions between STMN2+ TAMs and CD8+ Tex cells." (PMID 41438751, 2025). "To further assess the pan-cancer applicability of STMN2.SIG, we validated its ability of risk-stratification in IMmotion150, IMmotion151, Mariathasan, and Riaz cohorts." (PMID 41438751, 2025). "Within the Braun cohort, we evaluated the AUC of pan-cancer STMN2.SIG, several clinical variables, and the nomogram model, emphasizing pan-cancer STMN2.SIG’s superior predictive power." (PMID 41438751, 2025). "Calibration curves revealed a strong concordance between the signature’s predicted and observed probabilities, revealing the well consistency, accuracy and stability of pan-cancer STMN2.SIG." (PMID 41438751, 2025). "Our study provides pan-cancer STMN2.SIG as an outperforming approach for patient selection of immunotherapy, and advances our understanding of TAM biology and suggests potential therapeutic strategies for downregulation of BCAP31 in TAMs." (PMID 41438751, 2025). "The pan-cancer scRNA-seq and RNA-seq datasets were incorporated to develop the STMN2+ Macrophage Signature (STMN2.SIG), which predicts immunotherapy response based on integrative machine learning techniques." (PMID 41438751, 2025). "We subsequently conducted the confusion matrix to illustrate the high precision of pan-cancer STMN2.SIG." (PMID 41438751, 2025). "We subsequently employed the nomogram to integrate several clinical factors along with pan-cancer STMN2.SIG, facilitating clinical decision-making." (PMID 41438751, 2025). "Relative to existing immunotherapy related signatures, the pan-cancer STMN2.SIG achieved markedly higher AUC values in RCC patients, highlighting its superior predictive capacity for immunotherapy response in RCC patients." (PMID 41438751, 2025). "DCA curves in the Braun cohort further highlighted the net clinical advantage of pan-cancer STMN2.SIG, which outperformed other clinical predictors." (PMID 41438751, 2025). "In our study, we firstly pioneer the usage of large-scale pan-cancer scRNA-seq and RNA-seq immunotherapy datasets to develop and validate the pan-cancer STMN2.SIG for predicting immunotherapy response through ML approaches." (PMID 41438751, 2025). "Subsequently, we constructed a predictive model (pan-cancer STMN2.SIG) for immunotherapy response by leveraging diverse ML techniques and integrating comprehensive scRNA-seq and bulk transcriptomic data, thereby enhancing prediction accuracy and showcasing innovation." (PMID 41438751, 2025). "The expression of STMN2 was up-regulated in cancer group compared with the normal group." (PMID 32510146, 2020). "Our analysis demonstrated that STMN2+ TAM possibly influenced both immunotherapy responsiveness and patient prognosis in pan-cancer, as well as NB specific context." (PMID 41438751, 2025). "Cluster 7 included cells with aberrant neuronal identity that expressed neuronal development genes (NEFM, DCX, STMN2, HES6) but also cell cycle and cancer-related genes (CRABP2, CCND1, MYC)." (PMID 33771987, 2021). "Having validated the pan-cancer STMN2.SIG’s utility in predicting immunotherapy response, we next investigated its broader applicability in pediatric cancer prognosis, which is our research focus for pediatric surgeons, as frontline immunotherapy is not standard in NB." (PMID 41438751, 2025). "A higher proportion of STMN2+ TAMs was observed in non-responders compared to responders in pan-cancer immunotherapy landscape." (PMID 41438751, 2025). "Additionally, in the combined datasets of every cancer type, the pan-cancer STMN2.SIG demonstrated superior AUC values, with non-responders consistently showing higher risk scores." (PMID 41438751, 2025).
cancer (continued). "Furthermore, the pan-cancer STMN2.SIG exhibited enhanced predictive capabilities across the training, internal validation, and external validation datasets, as well as in the aggregated datasets of different cancer types." (PMID 41438751, 2025). "Additionally, the risk score is consistently higher in non-responders compared to responders across all cancer types, suggesting that STMN2+ TAM may significantly contribute to the failure of immunotherapy." (PMID 41438751, 2025).
neurodegenerative disease (8 papers, 2017 to 2025). A disorder of the central nervous system characterized by gradual and progressive loss of neural tissue and neurologic function. "The expression of the STMN2 cryptic exon clearly correlates with TDP-43 pathology in several neurodegenerative diseases." (PMID 40140908, 2025). "The improper splicing of the STMN2 has recently been connected to a variety of neurodegenerative diseases." (PMID 36009085, 2022). "Evidence to suggest that Wallerian-like processes occur in neurodegenerative diseases comes from recent studies in which the axon outgrowth and regeneration factor Stathmin 2 (also known as SCG10) was found to be downregulated in ALS spinal motor neurons." (PMID 31661035, 2019). "This work points to a novel mechanism by which this SSV may regulate STMN2 gene expression and could further explain the recently elucidated STMN2 cryptic exon mechanism and its influence on neurodegenerative disease phenotype." (PMID 35034660, 2022). "Together these analyses suggest that splicing alterations observed in STMN2 and ARHGAP32 likely resulted from TDP-43 dysfunction, whereas most of the other observed splicing alterations resulted from general neurodegenerative disease processes." (PMID 40478310, 2025). "Reduced STMN2 expression is found in sporadic ALS and C9ORF72-ALS/FTD and potentially in additional neurodegenerative diseases." (PMID 40140908, 2025). "As both STMN2 and TDP-43 affect mitochondrial dynamics, and neuronal mitochondrial dysfunction is a cardinal feature of many neurodegenerative diseases, this abnormality likely contributes to the observed motor deficit." (PMID 38562780, 2024).
neurological disease (2 papers, 2022 to 2023). "To evaluate cerebellar TDP-43 expression and function in FTLD-TDP, we analyzed TDP-43 protein levels and the splicing of a TDP-43 target, STMN2, in the cerebellum of 95 FTLD-TDP cases and 25 non-neurological disease controls." (PMID 35879741, 2022). "Nevertheless, these and other transcript‐level alterations warrant further investigation as candidate biomarkers, as supported by the recent reports of STMN2 and UNC13A in ALS post‐mortem tissue and the alternative splicing events seen in the peripheral blood of other neurological disorders." (PMID 37818590, 2023).
immune dysfunction (1 paper, 2025). "Our results revealed an important association across STMN2+ TAM scores and both immune dysfunction scores and T cell exhaustion scores." (PMID 41438751, 2025).
peripheral neuropathies (1 paper, 2025). "STMN2 has been implicated in peripheral neuropathies and motor denervation, which suggests that its decrease in DPN may contribute to axonal vulnerability." (PMID 40828619, 2025).
STMN2 also shares sentences with these, for which no sentence is quoted: gastric cancer (3 papers); adenocarcinoma (2); Down syndrome (2); glioma (2); Ataxia (1); bipolar disorder (1); breast carcinoma (1); Cervical (1); cholangiocarcinoma (1); choriocarcinoma (1); chronic hepatitis C virus infection (1); cognitive decline (1); fibrosis (1); Goldberg-Shprintzen syndrome (1); hereditary spastic paraplegia (1); Hirschsprung disease (1); infection (1); Insulin resistance (1); leiomyoma (1); lymph node metastasis (1); major depression (1); melanoma (1); motor neuron diseases (1); myeloma (1); pancreatic cancer (1); peripheral nerve injury (1); POEMS syndrome (1); primary effusion lymphoma (1); Salmonella Infections (1); schizophrenia (1).
A further 2 diseases each share a sentence with STMN2 in 1 paper.